INS (insulin)
Diseases named in the same sentence as INS in open-access papers (continued):
Sharing a sentence is not in itself a finding about the gene and the disease.
type 2 diabetes (continued). "A head-to-head randomised trial was conducted to evaluate hypoglycaemia safety with insulin degludec 200 U/ml (degludec U200) and insulin glargine 300 U/ml (glargine U300) in individuals with type 2 diabetes treated with basal insulin." (PMID 31984443, 2020). "A Dutch study of people with type 2 diabetes showed that the most significant predictors of low HRQoL were insulin use and the presence of complications." (PMID 33291678, 2020). "USA guidelines suggest that metformin should be discontinued and insulin should be started as soon as possible when pregnancy occurs in patients with type 2 diabetes." (PMID 32887578, 2020). "The role of EGF in adipogenesis is well-described with EGF receptor (ErbB1) abundance reduced in insulin resistant women with Type 2 diabetes." (PMID 32265830, 2020). "We found that many of these hub proteins have central roles in disease, such as insulin for both A1C measurement and Type 2 Diabetes, BRCA1 in Breast cancer, and Amyloid Precursor Protein in Alzheimer’s Disease." (PMID 32678846, 2020). "Subgroup analysis showed that those who were physically inactive, or had IFG or type 2 diabetes, experienced statistically significant greater glycaemic benefits from PA breaks, and attenuation of insulin also approached significance." (PMID 31552570, 2020). "Metabolic syndrome, type 2 diabetes, fasting insulin, AST, and ALT were included in this prediction model." (PMID 32899243, 2020). "In type-1 diabetes we can measure insulin levels but in type-2 diabetes we need the physiological read out of elevated blood sugar levels." (PMID 32373557, 2020). "Determining nutritional mediators which stimulate different molecular mechanisms of insulin signalling to generate these paradoxical effects provides insights into the obesity heterogeneity in Type II diabetes." (PMID 32670384, 2020). "Similar observations were documented for a mouse model with beta cell-specific knock-out of Tfb1m that resulted in lower insulin secretion, mitochondrial dysfunction, and eventual development of type 2 diabetes." (PMID 32765591, 2020). "Dapagliflozin, a novel inhibitor of renal sodium-glucose cotransporter 2, allows an insulin-independent approach to improve type 2 diabetes hyperglycemia." (PMID 33031329, 2020). "To conclude, Humalog U-200 is an appropriate therapeutic option for patients with type 2 diabetes who require insulin treatment to manage their hyperglycemia." (PMID 32002193, 2020). "The insulin resistance state of pancreatic α-cells seems to be related to glucagon hypersecretion in type 2 diabetes." (PMID 33020399, 2020). "For example, metformin, a drug commonly prescribed to type 2 diabetics, is an insulin sensitizer which targets complex I of the electron transport chain and has been proposed as a supplementary therapy for Mtb which targets host metabolism." (PMID 32984072, 2020). "The increased binding affinity of the activated ProINS-Tf to IR makes the fusion protein utilized valuable treatment option for INS-resistant type 2 diabetes, as well as other metabolic diseases." (PMID 32382087, 2020). "A chronic high level of insulin in blood circulation leads to the development of insulin resistance and type 2 diabetes in mice." (PMID 32722262, 2020). "As recommended by the guidelines of the China Diabetes Society7, 8, for newly diagnosed type 2 diabetes patients with HbA1c >9.0%, short‐term intensive insulin therapy can be implemented." (PMID 31161658, 2020). "H19 is significantly decreased in the muscle of humans with type-2 diabetes and insulin-resistant rodents, and this decrease is correlated with increased let-7 bioavailability." (PMID 33071823, 2020). "In type 1 diabetes beta cells are destroyed by autoreactive immune cells, while in type 2 diabetes the number or function of beta cells is compromised and insulin production is insufficient to cope with demand." (PMID 32978479, 2020).
type 2 diabetes (continued). "Type 2 diabetes is characterized by impaired insulin secretion resulting from dysfunction of the pancreatic β-cells and/or reduction in β-cell mass in addition to insulin resistance in peripheral tissues." (PMID 33294783, 2020). "S961 treatment in mice and rats has been shown to induce features of type 2 diabetes including hyperglycaemia, glucose intolerance and impaired insulin sensitivity." (PMID 32704569, 2020). "These pro-inflammatory cytokines interrupt normal signaling of insulin and β-cell function, which decreases symptoms of obesity and Type 2 diabetes." (PMID 32059381, 2020). "Type 2 diabetes is characterized by chronically elevated blood glucose levels, due to inadequate production of insulin and an inability of the body to effectively respond to insulin." (PMID 32641021, 2020). "Focusing on the natural history of type 2 diabetes progression, insulin secretion initially increases to compensate for peripheral insulin resistance." (PMID 31222973, 2020). "In addition, it was cautiously hypothesized that tai chi exercise might lead to the destruction of islet cell storage and insulin secretion, and there was a certain risk of converting type 2 diabetes into type 1 diabetes based on the significant decrease in C-P level after tai chi intervention." (PMID 33332396, 2020). "With the epidemic of obesity and type 2 diabetes, the number of people requiring high doses of insulin has been growing." (PMID 32396624, 2020). "Significantly, it also seems that the disruption of zinc homeostasis is correlated with impaired insulin sensitivity and signalling, as is often observed in both type 1 and type 2 diabetes." (PMID 33081637, 2020). "During early stages of type 2 diabetes, insulin‐mediated glucose uptake in the liver, muscle, and adipose tissue becomes less effective, a state named insulin resistance." (PMID 32512650, 2020). "Our results agree with a previous study showing that insulin enhances the transcription of p85α in human skeletal muscle cultures, but is blocked in the skeletal muscle of type 2 diabetic patients after a 3 h hyperinsulinaemic euglycaemic clamp." (PMID 31936857, 2020). "Another study assessed the effect of oral capsules containing Iranian propolis (three capsules/day for eight weeks; 500 mg per capsule) on blood glucose, insulin resistance, and antioxidant status in type 2 diabetes." (PMID 33383693, 2020). "Type-2 diabetes occurs when the pancreas cannot keep up with demand for insulin; ultimately the pancreatic islet beta cells die, the pancreas fails (insulin-dependent type-2 diabetes), and glucose levels rise." (PMID 32153503, 2020). "We assessed the associations and interactions between starch intake, AMY1 copies and glucose homeostasis traits (i.e., fasting plasma glucose, insulin and HOMA-IR) and risk of type 2 diabetes over an average of 18 follow-up years." (PMID 33490099, 2020). "Pramlintide is a Food and Drug Administration (FDA)-approved amylin analogue, developed for individuals with type 1 diabetes or insulin-treated type 2 diabetes as an adjunct therapy to mealtime insulin." (PMID 33488526, 2020). "When the nutrition load increases, insulin secretion decreases, leading to the development of diabetes type 2." (PMID 33490239, 2020). "The hepatocyte response to insulin is impaired in the insulin-resistant conditions leading to hyperglycemia, a pathological character of type 2 diabetes." (PMID 32440681, 2020). "In this respect, activation of novel PKCs has been shown to link fat accumulation with impaired insulin signalling in both animal models and individuals with type 2 diabetes." (PMID 32185462, 2020). "Blocks JNK-dependent Con A-induced liver damage; restores insulin sensitivity in mouse models of type 2 diabetes." (PMID 31994958, 2020). "They demonstrated that serum RBP4 level was higher in humans with obesity and type 2 diabetes as well as in insulin-resistant mice." (PMID 31690939, 2020).
type 2 diabetes (continued). "Possibly, flavonoids can significantly reduce the GLU4 transporter in adipocyte 3T3 to reduce oil droplets in adipocytes, thereby improving insulin sensitivity and glucose homeostasis in type 2 diabetic rats." (PMID 33149860, 2020). "Management of patients with type 2 diabetes typically begins with the initiation and titration of non-insulin glucose-lowering medications (NIGLM)." (PMID 33202616, 2020). "Regarding the food rich in n-3 PUFAs, the consumption of tree nuts, for example, almonds, reduces LDL cholesterol levels by 3 to 19%, while fish consumption has beneficial effects on insulin sensitivity, type 2 diabetes mellitus (T2DM), and lipid profile." (PMID 33228237, 2020). "When comparing the use of antidiabetic medicines other than insulin, survey participants corresponded well, on average, to Finnish patients with type 2 diabetes." (PMID 31665003, 2019). "Type 2 diabetes is characterized by insulin resistance of the tissues capable of capturing glucose and/or the lack of insulin production due to β–cell function decline." (PMID 31225503, 2019). "We also found that the expression level of Sac2 positively correlated with insulin secretion in both cell lines and human pancreatic islets and that the expression of Sac2 was reduced in islets isolated from patients with type 2 diabetes." (PMID 31533953, 2019). "Increased plasma BCAA and lipids can lead to the development of β-cell dysfunction, which can accelerate the transition from an obese, insulin-resistant state to metabolic syndrome and type II diabetes." (PMID 31387549, 2019). "Insufficient insulin action results in increased fasting glucose and eventually leads to overt type 2 diabetes." (PMID 31779625, 2019). "In contrast, during the second stage of type-2 diabetes, there is a failure of β-cells to secrete sufficient insulin for glycemic control, and thus hyperglycemia is manifest." (PMID 31178685, 2019). "In type 2 diabetes, there is both insulin insensitivity and resistance resulting in impaired glucose availability in cells to provide energy." (PMID 30944035, 2019). "Tyrosine kinase inhibitors used for treatment of malignancies have demonstrated improvement of glycaemia in cases of type 1 diabetes and type 2 diabetes, possibly by enhancing beta cell survival and insulin secretion." (PMID 31672146, 2019). "In the type 2 diabetes (T2D) model induced by a combination of HF and low doses of streptozotocin, AF lowered hyperglycaemia and improved insulin-stimulated glucose disposal." (PMID 31680948, 2019). "Type I diabetes is a form of autoimmune disease whereby the cells that produce insulin are destroyed by its own immune system whereas type II diabetes, being more common than type I, happens when the body does not respond to the insulin produced." (PMID 31470636, 2019). "Defects in pancreatic beta cells, and the action of insulin play an essential role in type 2 diabetes, one of the most common metabolic diseases occasioned by obesity." (PMID 31817583, 2019). "In type 2 diabetes (T2D), insufficient secretion of insulin from the pancreatic β-cells contributes to high blood glucose levels, associated with metabolic dysregulation." (PMID 31627434, 2019). "Currently, oral administrative drugs commonly used in the treatment of type 2 diabetes mainly include insulin secretion agents (sulfonylurea and glycine secretion), insulin sensitizers (biguanide and gliadin), and alpha-glycosidases." (PMID 30941199, 2019). "Type II diabetes is more predominant, and it results from insulin resistance in target tissues or the shortage in insulin secretion." (PMID 31191707, 2019). "Our study deciphers a compelling linkage between insulin resistance in type 2 diabetes and tau pathology observed in 4R-tauopathies including AD." (PMID 31427921, 2019). "Type 2 Diabetes which happens to be the non-insulin dependent one is the most common form of the disease and is caused by the interaction between genetic and non-genetic factors." (PMID 31803711, 2019).
type 2 diabetes (continued). "In type 2 diabetic animal models, glucose and glycated hemoglobin (HbA1C) blood levels and the ability of pancreatic β-cells to secret insulin are important indices for the evaluation of diabetes." (PMID 30841887, 2019). "Of interest, is that emerging therapeutic approaches of metabolic disease have recently shown to improve insulin sensitivity and cardiac function in type 2 diabetic patient and experimental models." (PMID 30626440, 2019). "Blood-based biomarkers, such as glucose, insulin and HbA1c are used in the diagnosis and management of type 2 diabetes and plasma lipoproteins in cardiovascular diseases." (PMID 31690986, 2019). "Most suffer from Type 2 Diabetes which features elevated blood glucose levels and an inability to adequately secrete or respond to insulin." (PMID 31831727, 2019). "Pancreatic islets contain five endocrine cell types (α,β,δ,ε, and γ), of which β cells, which secrete insulin, are gradually lost during type 2 diabetes (T2D)." (PMID 30670690, 2019). "It is recommended that all individuals with type 1 diabetes, and those with type 2 diabetes who are taking insulin and/or sulphonylureas, always check their glucose level two to three times prior to exercise to establish the direction of change in glucose." (PMID 31161377, 2019). "Insulin impairment and inflammation are two features common to type 2 diabetes and Alzheimer’s disease; however, the molecular and signaling interactions underlying this relationship are not well understood." (PMID 31892368, 2019). "Overall, six sisters of the maternal grandmother were diagnosed with type 2 diabetes at ages between 30 and 40 years, of whom three had been treated with insulin (for 3–10 years) and three were treated with oral antihyperglycemic drugs." (PMID 30968599, 2019). "In animal models of type 2 diabetes, these complexes have a significant potential to reduce blood glucose, insulin serum, HbA1c, triglyceride, and total cholesterol, while improving glucose tolerance." (PMID 31619721, 2019). "Autoimmune destruction of β-cells leads to type 1 diabetes, whereas failure of the β-cells to compensate with an increase in insulin secretion in the face of rising glucose levels leads to type 2 diabetes." (PMID 31590432, 2019). "The type 2 diabetes is characterized by high levels of blood sugar or glucose resulting from defects in insulin production, insulin action, or both." (PMID 30630432, 2019). "Fourteen patients within the obese group and one patient (treated with metformin) in the lean group had type 2 diabetes; thus, for the measurement of glucose and insulin and the calculation of HOMA-IR, these patients were excluded from analysis." (PMID 30719456, 2019). "The increased insulin secretion at 2.8 mM glucose observed in mutSorcs1 INS1 cells is also reminiscent of the elevated basal (pro)insulin secretion characteristic of Type 2 Diabetes, and indicative of dysregulated proximal insulin processing." (PMID 31857633, 2019). "Our previous study found that MSC infusion promoted macrophage polarization to the M2 phenotype in insulin-sensitive tissues and improved insulin sensitivity and alleviated hyperglycemia in type 2 diabetic rats." (PMID 31382970, 2019). "Expression of LGALS12 in adipocytes is up-regulated by PPAR-γ agonists suggesting its role in insulin signaling and type-2 diabetes." (PMID 31167428, 2019). "Studies demonstrate that postpartum insulin sensitivity is one of the strongest predictors of progression to type 2 diabetes following GDM in the first 5 years following the index pregnancy." (PMID 31002638, 2019). "To assess the possible co-regulation of the miRNAs of interest in the insulin signaling pathway and Type 2 diabetes signaling pathway we correlated the genes in these pathways with the miRNAs that were predicted to target them." (PMID 31222113, 2019).
type 2 diabetes (continued). "It enhances insulin action in human adipocytes in vitro and its circulating levels are decreased in individuals with obesity and/or patients with type 2 diabetes (T2D)." (PMID 31805941, 2019). "MITI is the first mHealth intervention designed to help patients with type 2 diabetes who need insulin adjustment." (PMID 31368439, 2019). "The insulin treatment of people with type 2 diabetes requires normalization of both fasting and postprandial glycemia." (PMID 30871141, 2019). "Approximately, there are 95% of diabetic patients with type 2 diabetes (T2D) that mainly illustrated by hyperglycemia due to the defects in insulin secretion, insulin action, or both of them." (PMID 31428203, 2019). "In the present study, we successfully established the HFD/STZ rat model mimicking human type 2 diabetes with impaired insulin secretion and insulin resistance." (PMID 31019978, 2019). "Decreased insulin signaling occurs in patients with type II diabetes, where higher insulin levels are often elicited, likely as a compensatory action." (PMID 30652125, 2019). "Our results suggest that if patients are treated as having type 2 diabetes but progress to insulin within 3 years of diagnosis, clinicians should reassess the underlying diagnosis and strongly consider biomarker testing." (PMID 30969375, 2019). "The aim of this study was to assess the impact of mealtime fast-acting insulin aspart therapy on glycemic variability as compared to regular human insulin therapy in advanced chronic kidney disease (CKD) patients with type 2 diabetes (T2D)." (PMID 31886089, 2019). "Current studies have shown that insulin enhancers play an important role in the treatment of type 2 diabetes and have great importance in the improvement of type 2 diabetes." (PMID 31072232, 2019). "Participants with type 1 diabetes and rapid insulin requirement were diagnosed younger compared to the participants with type 2 diabetes (median 27 vs 44 years, p < 0.001) and had a lower BMI (median 26 vs 34 kg/m2, p < 0.001)." (PMID 31558459, 2019). "In insulin resistant human subjects that are obese or have type 2 diabetes, insulin-stimulated glucose uptake by skeletal muscle is a primary site of dysfunction." (PMID 31075957, 2019). "This system can also be useful in people with type 2 diabetes to control the amount of food consumed or adjust insulin dosage." (PMID 30871141, 2019). "In the co-morbid conditions of obesity and type-2 diabetes, elevated adipocyte hypertrophy and enhanced inflammatory events are amongst the major detrimental factors that impair insulin signaling and deregulate glucose metabolism." (PMID 31888243, 2019). "Impaired insulin signaling is at the heart of why type 2 diabetes patients fail to regulate their blood sugar and is intimately linked with obesity." (PMID 32133436, 2019). "In these phase III studies the DPP-4 inhibitors were examined as monotherapy in drug-naïve patients and as add-on to on-going therapy with metformin, sulfonylurea therapy, thiazolidinedione therapy and therapy with exogenous insulin in type 2 diabetes." (PMID 31275243, 2019). "As insulin signaling has been established as an important player in ageing, our findings link ageing, AD, and type 2 diabetes, and indicate insulin signaling is the common underpinning of these biological phenomena." (PMID 30652125, 2019). "Down-regulated oxysterol-binding-protein-related 8 (ORP8) causes inhibition of insulin-dependent AKT phosphorylation and insulin resistance, a major cause of type 2 diabetes." (PMID 31817583, 2019). "Nevertheless, the IR-A is also expressed in various adult tissues under physiological conditions (e.g., brain) or pathological circumstances (e.g., insulin-target tissues in type 2 diabetes or cancer cells)." (PMID 31847392, 2019). "Considering type 2 diabetes adults, studies showed a reduction of body weight and increase insulin sensitivity with GBF consumption." (PMID 31146437, 2019).